ENSG00000257366 (microRNA 3180-2)
Gene: Long non-coding RNA gene on chromosome 16 (16,308,542 to 16,310,000, reverse strand). Ensembl gene ENSG00000257366.
Gene Ontology:
Biological process: miRNA-mediated post-transcriptional gene silencing